PFKP (phosphofructokinase, platelet)
Diseases named in the same sentence as PFKP in open-access papers (continued):
Sharing a sentence is not in itself a finding about the gene and the disease.
cancer (80 papers, 2013 to 2026). A tumor composed of atypical neoplastic, often pleomorphic cells that invade other tissues. "Determining the structure of human PFKP enabled 44 somatic mutations from cancers to be mapped onto it, leading to the prediction that 28 of these would affect activity, three of which were validated experimentally." (PMID 40329473, 2025). "One specific example is the PFKP mutation D564N—identified in colon cancer—which was shown to decrease enzyme activity but was proposed to favour cancer cell survival in tumour microenvironments where oxidative stress is present." (PMID 40329473, 2025). "For instance, PFKP, a key regulator of glycolysis, is implicated in metabolic reprogramming, a hallmark of cancer progression." (PMID 40817807, 2025). "PFKP is overexpressed in various types of cancers and its elevated expression is associated with poor prognosis." (PMID 38217030, 2024). "Violin plots displayed that higher expression of PFKP was associated with a lower immune score than low expression in 11 types of cancer." (PMID 37833332, 2023). "Second, to assess the role of PFKP in death caused by specific cancers, disease-specific survival (DSS) analysis was performed." (PMID 37833332, 2023). "More interestingly, GSEA results revealed that DEGs of PFKP had a strong correlation with hypoxia in 85% (28/33) of cancer types, an important hallmark of cancer." (PMID 37833332, 2023). "PFKP is a major isoform of cancer-specific phosphofructokinase-1 (PFK-1), which is linked to the first rate-limiting step of glycolysis." (PMID 30671168, 2018). "For example, PFKP, an estrogen signaling suppressive gene that encodes a rate-limiting enzyme of glycolysis, was downregulated in ER+ cancers." (PMID 23875016, 2013). "Moreover, PFKP-overexpressing cancer cells stimulate cancer-associated fibroblasts (CAFs), which in turn augment CD133+ CSLC formation via the CXCL16/CXCR6 axis, establishing a feedforward loop that reinforces chemoresistance." (PMID 42024199, 2026). "Cancer chemoresistance is associated with PFKP-mediated high glycolysis." (PMID 40264038, 2025). "All these data suggested that PFKP had a fine diagnostic value across cancers and could be exploited as a better diagnostic factor." (PMID 37833332, 2023). "Our pancancer data revealed that PFKP had a relative diagnostic accuracy in 13 cancer types, which suggested that PFKP could be a potential pancancer diagnostic biomarker." (PMID 37833332, 2023). "Increased PFKP could be one of the bypass signaling activations to maintain the low levels of glucose metabolism in ENO2-deficient cancer cells." (PMID 36588153, 2023). "A rate-limiting enzyme of glycolysis is called PFKP, which is essential for the metabolic reprogramming observed in cancer cells." (PMID 40821334, 2025). "Among these isoforms, the platelet-specific phosphofructokinase (PFKP) is highly expressed in various tumors and is considered a cancer-specific isoform." (PMID 40264038, 2025). "Since cancer cells have abnormally high glycolytic flux compared to normal cells, elevated PFKP expression is coherent with the situation to meet energy metabolism demands." (PMID 40821334, 2025). "HMG-CoA Reductase Degradation 1 (HRD1), as a metabolic enzyme, catalyzes the ubiquitination of PFKP and promotes its degradation, thereby inhibiting the expression and activity of PFKP in cancer cells and obstructing cell invasion and proliferation." (PMID 40134432, 2025). "As a key rate-limiting enzyme in cancer glycolysis, PFKP is appearing as a potential anticancer drug target." (PMID 40821334, 2025). "Only a handful of studies have explored the molecular mechanisms changing the expression of PFKP in cancer." (PMID 38217030, 2024). "Consistent with PFKP, the expression of c-Myc was higher in the cancer tissues than in their paired normal tissues." (PMID 38982480, 2024).
cancer (continued). "The aberrant expression of phosphofructokinase-platelet (PFKP) plays a crucial role in the development of various human cancers by modifying diverse biological functions." (PMID 38982480, 2024). "In this study, we demonstrated that the glycolytic enzyme PFKP is highly expressed in multiple types of cancers and significantly contributes to poor patient survival." (PMID 39664584, 2024). "Taken together, by combining DIA-MS, Co-IP, and RNA-seq analysis, we found that the metabolism and cancer-related signaling pathways were involved in PFKP regulation." (PMID 39664584, 2024). "PFKP (Phosphofructokinase, Platelet Type isoform), as an essential metabolic enzyme, contributes to the high glycolysis rates seen in cancers while its role in oncogenic pathways, especially from a non-metabolic aspect, is not fully understood." (PMID 39664584, 2024). "A substantial body of research has demonstrated the critical role of PFKP in promoting aerobic glycolysis within cancer cells, consequently driving cancer cell proliferation and metastasis." (PMID 38982480, 2024). "Aerobic glycolysis is a common feature of glucose metabolism in cancer cells, and PFKP is an important rate-limiting enzyme that regulates aerobic glycolysis." (PMID 38217030, 2024). "PFKP is a rate-limiting enzyme involved in aerobic glycolysis, which is overexpressed in various types of cancers." (PMID 38217030, 2024). "Then, the TNBC carcinoma tissue samples were stratified into two groups, according to high or low expression of the PFKP protein." (PMID 38217030, 2024). "Systematic bioinformation analysis of PFKP was performed based on several public datasets, including The Cancer Genome Atlas (TCGA), Cancer Cell Line Encyclopedia (CCLE), Genotype-Tissue Expression Project (GTEx), and Human Protein Atlas (HPA)." (PMID 37833332, 2023). "Phosphofructokinase platelet (PFKP) plays a crucial role in glycolysis regulation and is involved in human cancer progression." (PMID 37151384, 2023). "Our pancancer analysis data displayed that PFKP had a significant prognostic value among cancer patients." (PMID 37833332, 2023). "For example, the synthesis of 3-phosphoglycerate in MSI cancer cells depends on PFKP, a critical glycolytic pathway checkpoint." (PMID 36879264, 2023). "To assess the expression of PFKP in human cancer tissues, we first examined pancancer expression in the TCGA data repository." (PMID 37833332, 2023). "As the important enzyme of glycolysis, PFKP was observed to allow cancer cells to survive under metabolic stress." (PMID 37622118, 2023). "To further explore the drug prediction potential of PFKP, we assessed the effect of PFKP on the sensitivity of different cancer drugs." (PMID 37833332, 2023). "While PFKL and PFKM are enriched in liver and muscle, respectively, the third isoform, PFKP, is mainly expressed in platelet and also elevated in most human cancer cells." (PMID 37222403, 2023). "In summary, our data revealed that PFKP was highly expressed in most cancer types and was strongly correlated with poor patient prognosis." (PMID 37833332, 2023). "Concretely, a negative correlation between drug sensitivity to afatinib and PFKP expression was observed in 69.7% (23/33) of cancer types." (PMID 37833332, 2023). "In this paper, we extracted PFKP-related data by traversing diverse cancer-related databases, including The Cancer Genome Atlas (TCGA), Gene Expression Omnibus (GEO), Cancer Cell Line Encyclopedia (CCLE), and human protein atlas (HPA)." (PMID 37833332, 2023). "As observed in other cancers, the inhibition of PFKP expression decreased CRC cell growth and motility and impaired cell cycle progression." (PMID 37151384, 2023). "Previous studies have shown that PFKP mainly regulates cancer cell proliferation and metastasis by remodeling glycolysis." (PMID 37833332, 2023). "We propose that MSI cancer treatment regimens should include the use of glycolysis inhibitors to specifically target PFKP." (PMID 36879264, 2023).
cancer (continued). "Intriguingly, TRIM21 negatively regulates glucose metabolism in human cancers by modulating the degradation of regulators to promote the dysregulation of glycolysis, for example, promoting the degradation of PFKP and G6PD." (PMID 38092733, 2023). "Our data implied that patients with higher levels of PFKP had a lower sensitivity to several cancer drugs." (PMID 37833332, 2023). "Prospective carcinogenesis of PFKP across cancers was estimated by expression analysis, effect on patient prognosis, diagnosis significance evaluation, and immunity regulation estimation." (PMID 37833332, 2023). "In summary, PFKP overexpression contributes to CRC growth and invasion and PFKP expression can serve as a useful molecular biomarker for cancer prognosis and a potential therapeutic target for CRC." (PMID 37151384, 2023). "PFKP expression can serve as a valuable molecular biomarker for cancer prognosis and a potential therapeutic target for treating CRC." (PMID 37151384, 2023). "All these findings demonstrate that PFKP functions not only as a glycolysis enzyme, but more importantly as a potential oncogenic regulator in cancer." (PMID 35641476, 2022). "Since the intracellular energy and redox homeostasis is critical for cell proliferation and survival, we suspected that the PFKP-mediated long-chain fatty acid oxidation can promote cancer cell survival under GS." (PMID 35641476, 2022). "PFKP shows abnormal expression in many cancers and augments lactic acid production due to a high rate of glycolysis." (PMID 34831316, 2021). "PFKP is a rate-limiting enzyme involved in glycolysis that has been found to be upregulated in various types of cancer." (PMID 34869590, 2021). "In previous studies, PFKP is differentially expressed in glucose metabolic reprogramming in some cancers." (PMID 34595103, 2021). "Consistently, PFKP was upregulated in DKD patients compared with control renal tissues obtained from cancer patients, the result was surprising because PFKP was previously reported to be upregulated in cancer." (PMID 35095764, 2021). "Most cancer cells acquire energy mainly via a high rate of aerobic glycolysis in nourished condition, in which PFKP is the first rate‐limiting enzyme." (PMID 33107155, 2020). "Cancer cells mainly utilize the PFKP for glycolysis and Snail suppresses PKFP to redirect glucose flux into PPP, resulting in NADPH production via oxidative branch." (PMID 32927665, 2020). "The platelet isoform of PFK, PFKP, functions as an important mediator in cancer cell proliferation and metastasis." (PMID 31590367, 2019). "Activation of PFKP was reported in different cancers and targeted inhibition of PFK by azole derivative Clotrimazole showed inhibition in cancer cell proliferation, migration and glucose metabolism." (PMID 31638999, 2019). "Functionally, dynamic regulation of PFKP significantly potentiates cancer cell survival under metabolic stress and increases metastatic capacities in vivo." (PMID 28176759, 2017). "In this study, we found that Snail functions as a metabolic switch between aerobic glycolysis and PPP by repressing PFKP, a cancer-specific PFK-1, allowing cancer cell survival under metabolic stress." (PMID 28176759, 2017). "For another example, FBP1, an estrogen signaling responsive gene that encodes the enzyme catalyzing the reverse reaction of PFKP, was upregulated in the ER+ cancers, which could elevate the activity of the oxidative branch of the pentose phosphate pathway and thereby contribute to cancers." (PMID 23875016, 2013). "Previously reported studies showed the upregulation of PFKP in different cancers." (PMID 40821334, 2025). "Notably, HK-2, PFKP, and PKM2 are closely linked to cancer cells, exhibiting significant upregulation in tumors." (PMID 40832602, 2025).
cancer (continued). "Importantly, we demonstrated concomitantly high expression of USP5 and PFKP in TNBC patients with advanced TNM stage, highlighting that dysregulated USP5-PFKP signaling was functionally linked to cancer progression in TNBC." (PMID 38217030, 2024). "PFKP has an oncogenic role in cancer progression in vitro and in vivo." (PMID 39664584, 2024). "Although an increase in PFKP expression is a characteristic feature of malignant tissues, little is known about how PFKP expression is regulated during the development and progression of cancers." (PMID 38217030, 2024). "Studies have demonstrated that the expression of PFK-1 in cancer cells is often markedly elevated and that the compositions of PFK isozymes are also frequently altered with PFKL and PFKP typically being expressed at higher levels in cancer cells compared with PFKM." (PMID 38388430, 2024). "A positive relationship between them was observed in several types of cancer, suggesting that a high level of PFKP may predict a poor outcome in patients with cancer." (PMID 37833332, 2023). "First, our data found that promoter DNA methylation may play a partial regulatory role in high levels of PFKP across many cancer types." (PMID 37833332, 2023). "Additionally, immunohistochemistry of PFKP across cancers also displayed a cytoplasmic location of PFKP." (PMID 37833332, 2023). "Except for CRC, the biological function of PFKP was be clear examined in human cancer." (PMID 37151384, 2023). "Moreover, we also found that KIRC had the highest level of PFKP, while the lowest cancer type was LIHC, which was in accordance with its expression pattern in normal tissues." (PMID 37833332, 2023). "We also found an obvious immune-regulating effect of PFKP in most cancer types." (PMID 37833332, 2023). "Furthermore, to explore the regulation proficiency of these TFs, the expression correlation between PFKP and these predicted TFs was assessed across cancers." (PMID 37833332, 2023). "This pancancer analysis revealed that a high expression level of PFKP might be a useful biomarker and predictor in most cancer types." (PMID 37833332, 2023). "All these data suggested that PFKP has important clinical significance and may be a better prognostic factor across cancers." (PMID 37833332, 2023). "To date, few studies have focused on the relationship between PFKP and cancer drugs." (PMID 37833332, 2023). "In our analysis, we also detected the subcellular location of PFKP in different cancer cells." (PMID 37833332, 2023). "In conclusion, this study mainly summarized the role of PFKP and demonstrated that PFKP may be a candidate proto-oncogene and could be explored as a therapeutic target in most cancer types." (PMID 37833332, 2023). "The unclear mechanism of PFKP-mediated cancer growth and metastasis is a weakness of our study." (PMID 37151384, 2023). "Additionally, the performance of PFKP across cancers also suggested its meaningful role in cancer immunity regulation, even in immunotherapy and drug resistance." (PMID 37833332, 2023). "Our analysis revealed that high expression of PFKP was found in most cancer types." (PMID 37833332, 2023). "First, we assessed the overall survival data of PFKP across cancers." (PMID 37833332, 2023). "A high level of PFKP was closely correlated with poor prognosis in cancer patients." (PMID 37833332, 2023). "Additionally, a high level of PFKP displayed a significant correlation with poor prognosis in patients across cancers." (PMID 37833332, 2023). "A significant positive correlation between PFKP and PD-L1 suggested that PFKP may be involved in immune cell infiltration across cancers." (PMID 37833332, 2023). "Moreover, most cancer cell lines displayed higher levels of PFKP, which was common with normal tissues and indicated an important role across different cancer types." (PMID 37833332, 2023).
cancer (continued). "Additionally, a heatmap revealed that chemokines, including the C-X3-C motif chemokine ligand family, semaphorin chemokine family, and slit guidance ligand family, had a significant correlation with PFKP across cancers." (PMID 37833332, 2023). "Our study presented a positive correlation between them across cancers, which suggested that PFKP could be developed as a pancancer prognosis predictor." (PMID 37833332, 2023). "As PFKP Y64 phosphorylation regulates PI3K/AKT in EGFR-activated cancer cells, we investigated whether PFKP Y64 phosphorylation could modulate SP1 activity." (PMID 36435833, 2022). "As our data suggested that Fbxo7 increases PFKP activity, we tested whether Fbxo7 affected glycolysis in cancer cell lines using an Agilent Seahorse to measure the glycolytic rate." (PMID 35670764, 2022). "Lastly, whether the PFKP-AMPK signaling pathway could serve as a potential therapeutic target in cancer, especially in NSCLC, remains to be further investigated." (PMID 35641476, 2022). "The development of PFKP inhibitors may suppress the oncogenic function of PFKP in cancer, but more experiments are needed to validate this hypothesis." (PMID 35641476, 2022). "Besides, studies have also shown that PFKP can affect the proliferation of cancer cells through the glycolytic pathway." (PMID 33619234, 2021). "As a major isoform of PFK-1 in cancer glycolysis, PFKP has become an emerging anticancer target." (PMID 35095764, 2021). "PFKP (phosphofructokinase, platelet) is an isoform of phosphofructokinase, which plays a vital role in glycolysis regulation and metabolic reprogramming in many cancers including ccRCC 35,36." (PMID 32742447, 2020). "To confirm the Snail-PFKP axis, we designed an experimental system in which modulation of PFKP could rescue metabolic reprogramming and cancer cell survival regulated by Snail." (PMID 28176759, 2017). "Thus, PFKP isoform is a major PFK-1 controlling the first rate-limiting step of aerobic glycolysis in human cancer cells." (PMID 28176759, 2017). "We next examined the regulatory role of PFKP in metabolic reprogramming and cancer cell survival." (PMID 28176759, 2017). "Thus, the Snail-PFKP axis plays an important role in cancer cell survival via regulation of glucose flux between glycolysis and PPP." (PMID 28176759, 2017). "Importantly, recent determination of mammalian PFKP crystal structure can provide us with tremendous help in therapeutic targeting the enzyme to control aerobic glycolysis in different cancers." (PMID 27049827, 2016). "Considering the compelling evidence regarding IL-1β-mediated regulation of HIF-1α, a key regulator of PFKP and the glycolysis pathway in cancer cells, we further dissected if the IL-1β-HIF-1α signaling cascade is involved in ABCB5-mediated regulation of glycolysis." (PMID 27560924, 2016). "By contrast, PFKP is upregulated in the ER− cancers, which could accelerate the rate-limiting step of the anaerobic glycolysis subpathway." (PMID 23875016, 2013). "Therefore, the upregulation of PFKP also contributes to ER− cancers through the anaerobic glycolysis subpathway." (PMID 23875016, 2013). "Moreover, PFKP participates in cancer metastasis by regulating lactate production." (PMID 40821334, 2025). "It signifies that PFKP expression may have potential prognostic roles in cancer pathogenesis." (PMID 40821334, 2025). "In addition, USP5 has been reported to stabilize glycolytic enzymes such as PFKFB4 and PFKP in cancer, raising the possibility that similar mechanisms may exist in RA." (PMID 41339332, 2025). "Additionally, the link between PFKP and c-Myc has also been reported in other cancer types." (PMID 38982480, 2024). "Similarly, GSEA also indicated that PFKP may be involved in cancer metastasis by regulating EMT, which was also previously reported by Nam Hee Kim31." (PMID 37833332, 2023).